MIR4318 (microRNA 4318)
Synonyms: hsa-mir-4318
Gene: MicroRNA gene on chromosome 18 (37,657,135 to 37,657,215, forward strand). Ensembl gene ENSG00000266530.
Diseases named in the same sentence as MIR4318 in open-access papers:
MIR4318 is named in the same sentence as 1 disease in open-access papers, as found by Europe PMC text mining. Sharing a sentence is not in itself a finding about the gene and the disease.
MIR4318 shares sentences with these, for which no sentence is quoted: glioma (1 paper).